FAM114A2 (family with sequence similarity 114 member A2)
Synonyms: C5orf3; 133K02
Tractability: PROTAC: ubiquitination databases record sites on it; its protein half-life has been measured.
Gene: Protein-coding gene on chromosome 5 (153,990,148 to 154,038,936, reverse strand). Ensembl gene ENSG00000055147.
Subcellular location (Human Protein Atlas): Vesicles
Pathways (Reactome):
Disease: Signaling by BRAF and RAF1 fusions
Gene Ontology:
Molecular function: protein binding; purine nucleotide binding
Genetic constraint (gnomAD): Loss-of-function variants: 24 observed, 29.21 expected, observed/expected ratio (o/e) 0.82, 90% interval 0.59 to 1.15. The upper end of that interval is the gene's LOEUF score, 1.15, which puts it in group 5 of 6, group 1 being the genes least tolerant of losing a copy. Missense variants: 342 observed, 351.22 expected, observed/expected ratio (o/e) 0.97, 90% interval 0.89 to 1.07. Synonymous variants: 136 observed, 134.13 expected, observed/expected ratio (o/e) 1.01, 90% interval 0.88 to 1.17.
Homologues: Orthologues: chimpanzee FAM114A2 (99% identical), macaque FAM114A2 (98% identical), rabbit FAM114A2 (85% identical), dog FAM114A2 (84% identical), pig FAM114A2 (83% identical), guinea pig FAM114A2 (81% identical), rat Fam114a2 (80% identical), mouse Fam114a2 (79% identical), tropical clawed frog fam114a2 (55% identical), zebrafish fam114a2 (51% identical), Drosophila melanogaster CG9590 (22% identical). Paralogues in human: FAM114A1 (43% identical).
Diseases named in the same sentence as FAM114A2 in open-access papers:
FAM114A2 is named in the same sentence as 6 diseases in open-access papers, as found by Europe PMC text mining. Sharing a sentence is not in itself a finding about the gene and the disease. The quoted sentences say what the papers report.
melanoma (1 paper, 2014). A malignant, usually aggressive tumor composed of atypical, neoplastic melanocytes. "A number of BRAF fusions are, however, novel, including ATG7–BRAF in melanoma, as well as ZC3HAV1–BRAF and FAM114A2–BRAF in thyroid cancer." (PMID 25204415, 2014).
urothelial carcinoma (1 paper, 2021). A malignant neoplasm derived from the transitional epithelium of the urinary tract (urinary bladder, ureter, urethra, or renal pelvis). "Additionally, we also found that FAM114A2 mRNA was downregulated in urothelial carcinoma tissue and cell lines." (PMID 34722233, 2021).
FAM114A2 also shares sentences with these, for which no sentence is quoted: bladder cancer (2 papers); tumor (2); ankylosing spondylitis (1); thyroid cancer (1).